SPHK1 (sphingosine kinase 1)
Diseases named in the same sentence as SPHK1 in open-access papers (continued):
Sharing a sentence is not in itself a finding about the gene and the disease.
cancer (continued). "SphK1 plays a central role in NEPC development, which offers a new target for this lethal cancer using clinically approved SphK1 inhibitors." (PMID 35184376, 2022). "SphK1 can be targeted and silenced by miRNAs in various cancer cells to produce significant anti-cancer cell activity." (PMID 33465049, 2021). "Contrary to the notion that SphK2 has apoptotic functions, several experimental studies have suggested an essential role of this isoenzyme in cell proliferation and survival similar to SphK1 in cancer cells." (PMID 33920887, 2021). "Two distinct SPHK isoforms, namely SPHK1 and SPHK2, have been identified to date, and the former has been implicated for its oncogenic roles in cancer development and progression." (PMID 34820423, 2021). "Patients afflicted with cancers that had increased SphK1 mRNA expression were found to have worse prognosis and survival outlooks." (PMID 34069611, 2021). "Silencing SphK1 expression with specific miRNAs has proven to be an appropriate strategy to produce significant anti-cancer cell activity." (PMID 33465049, 2021). "Recently, SPHK1 has attracted increasing attention because of its important functions in many processes of cancer cells." (PMID 33660008, 2021). "Activated SphK1 catalyzes the conversion of sphingosine and ceramide to S1P, thus help achieving the cancer-promoting outcomes." (PMID 33465049, 2021). "With respect to the SphK-S1P signalling axis, it is possible that nuclear translocation of signalling components such as SphK1 and S1P3 in cancer cells facilitates pathogenic progression." (PMID 33919234, 2021). "We focused on SphK1 because it plays important roles in signal transmission and cancer proliferation." (PMID 33931106, 2021). "But it is exciting that the patent mainly states the treatment of these SphK1 inhibitors for cancer and RA, which makes people look forward to the research on mechanism and pharmacological activity in the near future." (PMID 34737701, 2021). "Multiple studies have illustrated that the targeted inhibition of SphK1 activity can be considered a potential strategy to combat cancer." (PMID 33920887, 2021). "The elevated intracellular SphK1 levels appear to play an essential role in uncontrolled cell proliferation and metastasis in various cancer cell types." (PMID 33920887, 2021). "A meta-analysis of SPHK1 in human cancers has demonstrated significantly higher levels of SPHK1 in both benign and cancerous tissues as compared to normal tissues." (PMID 34820423, 2021). "In these malignancies, SPHK1 commonly functions as an oncogene which promotes cancer metastasis and invasion." (PMID 33506044, 2021). "For example, MP-A08 reduces S1P levels via selectively targeting the ATP-binding site of SphK1 and SphK2, leading to inhibition of cancer cell proliferation and apoptosis induction." (PMID 35201458, 2021). "Previous studies have suggested that SPHK1 played an important role in tumorigenesis and cancer progression." (PMID 33506044, 2021). "In recent years, SphK1 has been increasingly recognized as a major driver of various inflammatory diseases and cancers, and there is great interest in inhibiting over-expression of human SphK1 (hSphK1) as an anticancer therapy." (PMID 34737701, 2021). "There is substantial evidence suggesting the crucial role of dysregulated SphKs (specifically SphK1) along with a transformed signaling mechanism, in cancer development." (PMID 35201458, 2021). "Several researchers have reported that SPHK1 is overexpressed in various types of cancer, whereas a higher PKR content results in a more favorable prognosis." (PMID 32801355, 2021).
cancer (continued). "For example, fingolimod (FTY720) SPHK1 selective inhibitor is widely used as an anti-sclerotic drug which activates protein phosphatase 2A and suppresses cancer cell growth." (PMID 34502095, 2021). "SphK1 expression is found to be elevated in malignant pleural mesothelioma, a resistant form of cancer that develops in the lining of the lungs." (PMID 33920887, 2021). "E2F1, a transcription factor shown to be involved in the cellular proliferation of cancer cells, binds to the promoter region of SPHK1 to increase transcription, thus increasing sphingosine kinase and consequently S1P." (PMID 34071409, 2021). "The over-expression of SphK1 (a lipid kinase) and its metabolite S1P have been observed in various types of cancer and metabolic disorders, making it a potential therapeutic target." (PMID 33920887, 2021). "Abnormal SphK1 has also become the research direction of a variety of diseases due to the discovery of over-expression of SphK1 in cancer." (PMID 34737701, 2021). "SK1-I is a competitive and selective SphK1 inhibitor with Ki value of 10 μM, and has been widely used to elucidate the role of SphK1 in cancer." (PMID 34737701, 2021). "As a lipid kinase that phosphorylate sphingosine to S1P, SphK1 involves many physiological and pathophysiological processes, but are especially active in cancer cells where they can promote proliferation, migration, invasion, and metastasis." (PMID 34268882, 2021). "Studies have shown that SphK1, which is essential for cancer cell survival, apoptosis resistance and migration, is overexpressed and/or hyper-activated in NSCLC." (PMID 34178653, 2021). "The translocation of activated SPHK1 to plasma membrane leads to the generation of S1P, which subsequently acts as a bioactive sphingolipid to regulate cancer cell growth and metastasis." (PMID 34820423, 2021). "The results of qRT-PCR showed that the mRNA expression of INHBA and SPHK1 were significantly increased in cancer than in normal tissues and cells." (PMID 34692520, 2021). "The up-regulation of SphK1 is seen in many human cancers, pointing out the possibility that its overexpression accompanied a rise in S1P synthesis that accounts for the pro-inflammation in the tumor microenvironment." (PMID 33920887, 2021). "FTY720 shows anticancer properties via diverse mechanisms; a widely studied one involves the inhibition of SphK1, whose up-regulation leads to cancer progression, migration, and metastasis." (PMID 33920887, 2021). "In cancer cells, sphingosine kinase 1 (SPHK1) is activated by reactive oxygen species (ROS) and increases AKT activity under hypoxia, eventually stabilizing HIF-1α proteins." (PMID 34575983, 2021). "Multiple human cancers harbor the SK type 1 isoform that is coded by the gene SPHK1, and is responsible for the high levels of S1P." (PMID 33670011, 2021). "The interplay between the SphK1/S1P/S1PR signal and estrogen-related receptors was implicated in cancer invasion and chemoresistance." (PMID 34831211, 2021). "It is possible that the heterogeneous findings regarding SphK1 and S1P3 localization in cancer are reflective of underlying cellular heterogeneity." (PMID 33919234, 2021). "In the next part of this review, we focus on the current knowledge of SphK1/S1P signaling in various cancer types and other human pathologies." (PMID 33920887, 2021). "Consistent with our previous study, it was found that in many human cancers, including EOC, SphK1 expression was significantly increased and promoted cancer development via cancer angiogenesis and metastasis." (PMID 32796926, 2020). "Sphingosine kinase 1 (SphK1) is one of the well-studied drug targets for cancer and inflammatory diseases." (PMID 32526899, 2020). "In contrast to the well-studied oncogenic roles of SphK1 in cancer progression, the roles of SphK2 remain controversial for both pro-apoptotic and pro-survival functions have been suggested." (PMID 32796926, 2020).
cancer (continued). "One promising strategy to inhibit SphK1-induced cancer progression is to express SphK1-targeting miRNAs." (PMID 32203055, 2020). "We identified STAT1 and IFN signaling as key regulatory targets of SPHK1 and demonstrated that an important mechanism by which SPHK1 promotes cancer cell survival is through the suppression of STAT1." (PMID 32260399, 2020). "Sphingosine kinase 1 (SphK1) accounts for triggering cancer chemoresistance and also, elevating glycolysis." (PMID 33187385, 2020). "Higher expression of SphK1 in cancer tissues in comparison to normal surrounding colonic mucosa was confirmed by immunohistochemistry analysis of CRC patient tissue samples." (PMID 32456134, 2020). "The expression of SPHK1 is increased in various cancers, including breast cancer, gastric cancer, colon cancer, glioblastoma tissues, and cells, facilitating tumor growth." (PMID 33260606, 2020). "Recently discovered small-molecule inhibitors of SphK1 have been recommended in cancer therapeutics; however, selectivity and potency of first-generation inhibitors are great challenge." (PMID 32526899, 2020). "The two isoforms of SphK, SphK1 and SphK2, are involved in regulating physiological and pathological processes, including cancer progression." (PMID 32796926, 2020). "SphK1 promotes V12Ras-dependent transformation and the growth and survival of cancer cells while inhibiting apoptosis and conferring resistance to γ-irradiation and chemotherapeutic agents." (PMID 32456134, 2020). "Sphingosine kinase 1 (SphK1) is increased in many types of human cancers and has been recognized as a contributing factor in carcinogenesis, chemoresistance and poor patient outcome." (PMID 32456134, 2020). "SphK1 promotes cancer cell viability, proliferation, and apoptosis resistance, as well as metastasis, and angiogenesis." (PMID 32371868, 2020). "Considerable attention has been devoted to the involvement of SphK1 in multiple cancers including HCC." (PMID 32670862, 2020). "Sphingosine kinases remain targets of interest for cancer therapy, and inhibitors of both SphK1 and SphK2 have been investigated in clinical trials." (PMID 32521763, 2020). "For examples, SphK1 counteracts ceramide-induced apoptosis, constituting the basis of cancer drug resistance." (PMID 33633691, 2020). "SphK1 inhibition will lead to ceramide (and sphingosine) accumulation, mediating cancer cell apoptosis." (PMID 33154352, 2020). "Several studies have indicated that increased SPHK1 activity promotes cancer cell growth, metastasis, and inhibits apoptosis." (PMID 32260399, 2020). "A variety of sphingolipid based and nolipidic small molecule inhibitors of SphK1 have been reported and have shown cytotoxic effects in several resistant cancer cell lines." (PMID 31752564, 2020). "S1P generated by the catalytic action of SphK1 acts as pro-survival molecule and activates downstream targets involved in diverse pathological processes like cancer initiation, progression and inflammation." (PMID 31822735, 2019). "In these networks, PTGS2, VDR, RHOB, PIM1, HSPA1L, HSPA1A, and SPHK1 were used as targets for cancer drug development, previously." (PMID 30842898, 2019). "In conclusion, we infer that quercetin and capsaicin provide a chemical scaffold to develop potent and selective inhibitors of SphK1 after required modifications for the clinical management of cancer." (PMID 31822735, 2019). "SPHK1 plays an important role in tumorigenesis, hormonal therapy, chemotherapy resistance, and it is considered to be a new target for cancer therapeutics." (PMID 31138124, 2019). "Overall, SPHK1/2 are inflammatory, and hence inhibition of SPHK1/2 decreases cancer-mediated inflammation." (PMID 31817453, 2019). "Owing to its remarkable role in cancer progression and metastasis, and other inflammatory diseases, SphK1 presents a novel therapeutic target to develop effective therapeutics to combat these diseases." (PMID 31822735, 2019).
cancer (continued). "One of the key cancer-related findings indicated that adipokine leptin stimulated expression of SphK1 in ER-negative breast tumors." (PMID 29385066, 2018). "There has been an accumulating body of evidence that SphK1 is critically involved in cancer development since we first reported the oncogenic potential of SphK1." (PMID 29643998, 2018). "Apparently, estrogen not only regulates sphingolipid composition and signaling in cancer cells, but also intensifies SphK1 expression." (PMID 29385066, 2018). "It has been widely reported that SphK1 promotes cancer growth via direct stimulation of proliferation and survival pathways." (PMID 29643998, 2018). "Further analysis demonstrated that nuclear presence of SphK1 is largely detrimental and significantly shortens disease-specific survival and accelerates cancer recurrence." (PMID 29385066, 2018). "In Katsuta et al48 study, it suggested that the expression of sphingosine kinase 1 tended to be higher in doxorubicin‐resistant human cancer and cell lines." (PMID 29923327, 2018). "In another study, SPHK1 was shown to be highly expressed in the tumor stroma of HGSOC and required for the differentiation and tumor promoting function of cancer-associated fibroblasts." (PMID 31891125, 2018). "It was further suggested that SphK1 can contribute to the development of anti-cancer drug resistance." (PMID 29385066, 2018). "In accordance, anticancer regimens have been shown to down-regulate SphK1 activity in various cancer cell and animal models." (PMID 30037082, 2018). "In general, SphK1 is tumor promoting and SphK2 is suppressive; SphK1 is upregulated in cancer, while SphK2 is downregulated." (PMID 29987226, 2018). "Inhibiting the Sphk1 activity leads to a decrease in cancer proliferation and metastasis in mouse models and increases the efficacy of chemotherapy and radiotherapy." (PMID 29718989, 2018). "There is now supporting evidence to suggest that aberrant expression and/or inappropriate cellular localization of SphK1 and SphK2 isoforms contribute to both oncogenicity and anti-cancer treatment resistance." (PMID 28415564, 2017). "Recent studies have also shown that Sphk1/S1P signaling is a preventive and therapeutic target for cancers." (PMID 28991193, 2017). "Particularly, PI3K/AKT pathway is better understood than SPHK-1 pathway in a hypoxic environment in cancer development." (PMID 28165392, 2017). "Although early studies have proposed a possible pro-apoptotic/anti-cancer function by of SphK2, emerging recent evidences have confirmed that SphK2, like SphK1, is also oncogenic." (PMID 29285269, 2017). "Treatment of DU145cells with SPHK1 siRNA and CA for 48 h decreased cancer cell growth, and the inhibitory action of SPHK siRNA and CA on cell growth was confirmed by decrease in the abundance of Proliferating cell nuclear antigen (PCNA)." (PMID 28165392, 2017). "There is a strong drive for SphK2 inhibitors given that they appear to be more efficacious than SphK1 inhibitors in in vitro cancer cell line studies and cancer clinical trial studies, in particular the SphK2 inhibitor ABC294640." (PMID 28869494, 2017). "Wilcoxon matched-pairs signed rank test demonstrated that SphK1 intensity was higher in cancer than adjacent normal tissues (cancer vs. adjacent normal, 1.10 ± 0.30 vs. 1.00 ± 0.00, P = 0.02)." (PMID 28583134, 2017). "Several studies including our group demonstrated that SphK1 deficiency inhibits the growth of polyps induced by an adenomatous polyposis coli (APC) mutation, AOM-induced ACF formation and AOM/DSS-induced cancer development." (PMID 28583134, 2017). "For instance, the increased Sphk1/S1P facilitates cancer cell proliferation, mobility, angiogenesis, invasion, and metastasis." (PMID 28991193, 2017). "A number of studies indicate that alterations of PP2A and SphK1 (namely, inhibition of the former and overexpression of the latter) cooperate in the activation of pro-survival pathways in cancer." (PMID 28298211, 2017).
cancer (continued). "In particular we review how aberrant expression of the hSphK1 isoforms can confer resistance to SphK1 targeted drugs highlighting the challenges faced in anti-SphK drug treatment in cancer therapy." (PMID 28415564, 2017). "Subsequently, the increased Sphk1/S1P facilitates cancer cell proliferation, mobility, angiogenesis, invasion, and metastasis." (PMID 28991193, 2017). "It is important to note that along with SphK1, SphK2 is overexpressed in many human cancers and based on its cellular localization it can function as a pro- or antiapoptotic signaling molecule." (PMID 29269995, 2017). "Over-expression and/or sustained-activation of SphK1 contributes to cancer cell progression and apoptosis-resistance." (PMID 28081222, 2017). "Although the SPHK–S1P axis is involved in many aspects of cancer progressions, the specific areas modulated by SPHK1 should be clarified in future studies." (PMID 29208982, 2017). "There is undisputable evidence to support a significant role for aberrant SphK1 and SphK2 isozyme expression in cancer development." (PMID 28415564, 2017). "This review updates our current knowledge of the SphK isozymes and highlights recent findings on the two prominent isoforms, SphK1a and SphK1b, and potential implications for efficacy of SphK1 directed cancer drug administration and outcome." (PMID 28415564, 2017). "Here we present an overview of hSphK1 and hSphK2 isozymes and an alternative perception of hSphK2 as a more efficient target for anti-cancer therapy compared to SphK1." (PMID 28415564, 2017). "SphK1 has emerged as a significant signaling enzyme because it contributes to the growth, metastasis and chemoresistance of various human cancers." (PMID 29088837, 2017). "In contrast, knocking down SphK1 by shRNA targeting human Sphk1 suppressed cancer cell viability and invasiveness, but facilitated cell apoptosis." (PMID 28991193, 2017). "Conversely, downregulation of SPHK1 in cancer cells enhanced apoptosis and chemosensitivity, with subsequently reduced tumor growth." (PMID 28804221, 2017). "Elevated cellular SphK1 levels appear to play a major role in enhanced proliferation and metastasis/invasion of several types of cancer cells." (PMID 28878674, 2017). "SphK1 is overexpressed in multiple types of cancers, which appears to contribute to carcinogenesis, chemo‐ or radioresistance, and poor prognosis." (PMID 28672103, 2017). "In this context, more than one study has demonstrated that inhibition of SphK1 has considerable potential as an anti-cancer strategy." (PMID 28878674, 2017). "SphK1 inhibitors, alone or in combination with conventional anti-cancer agents, have demonstrated promising anti-tumor results." (PMID 28206952, 2017). "In the main, this is due to the overwhelming evidence in cancer clinical patient analyzes showing overexpression of SphK1 and the initial findings by Xia and colleagues that provided the evidence of SphK1 being oncogenic." (PMID 28869494, 2017). "SphK1 activation positively regulates cancer cell survival, proliferation, transformation, as well as apoptosis prevention and chemo-resistance." (PMID 28206952, 2017). "Groups including ours have confirmed the important role of SphK1 in promoting cancer cell progression." (PMID 28206952, 2017). "Extensive studies from mouse models and cancer cell lines have placed SphK1 as a target for cancer therapy." (PMID 28415564, 2017). "In turn, SphK1 and S1P have been shown to promote tumor growth, tumor angiogenesis, metastasis, and resistance to apoptosis in several cancers." (PMID 28672103, 2017). "S1P is also considered as a cancer‐promoting molecule, as the upregulation of SphK1 is a common phenomenon in several cancers and correlates with poor prognosis." (PMID 28672103, 2017). "Several studies have demonstrated that SPHK-1 controls the level of HIF-1α during hypoxia in cancer cells." (PMID 27581969, 2016).